GSK3B (glycogen synthase kinase 3 beta)
Diseases named in the same sentence as GSK3B in open-access papers (continued):
Sharing a sentence is not in itself a finding about the gene and the disease.
depression (continued). "In agreement with a mechanistic role of GSK3 in mood disorders, GSK3β was found to be reduced and less phosphorylated in the prefrontal cortex of post-mortem brain samples of patients with depression." (PMID 37807001, 2023). "The effects of GSK3β inhibition on HSPA12A-maintained lactate production in hippocampal neurons prompted us to determine the effects of GSK3β inhibition on depression and anxiety behaviors in Hspa12a−/− mice." (PMID 37580315, 2023). "It has been showed that a significant increase in the activation of GSK-3β has been found in postmortem brain regions of depression patients." (PMID 37881439, 2023). "Our results show that mTOR and GSK3β signaling was profoundly altered in the chronic depression model used in this study, and that fluoxetine reversed in part these alterations in normal mice but not in OCT2 mutants." (PMID 37775532, 2023). "The total amount of GSK3β in PBMCs was significantly lower in patients with bipolar disorder than in patients with unipolar depression." (PMID 37807001, 2023). "Gestational stress induced anxiety and depression-like behaviors during the postpartum period, increasing Sema3A expression while decreasing that of phosphorylated GSK3β as well as c-Fos in the hippocampus." (PMID 36776771, 2022). "Another clinical study noted that the kinase activity of GSK-3β was significantly in the ventral prefrontal cortex of patients with major depression, while the activity of Akt was reversed." (PMID 35923544, 2022). "As GSK3β and CRMP2 were linked to major depression, we examined the mRNA and protein levels of GSK3β and CRMP2 in the hippocampus." (PMID 36776771, 2022). "Silencing of glycogen synthase kinase (GSK)-3β in the nucleus accumbens (NAc) increases depression- and addiction-related behavior." (PMID 36172262, 2022). "In the present study, we show how the intraventricular administration of meridianins is capable of modulating GSK3β activity in several brain regions involved with stress and major depression." (PMID 36286471, 2022). "Protein kinase B (AKT)/GSK3β/CRMP2 signaling was shown to be involved in the development of depression induced by stress." (PMID 36776771, 2022). "Then, we verified that meridianins can regulate in vivo GSK3β activity in different brain areas related to stress-related pathologies such as major depression disorder (MDD)." (PMID 36286471, 2022). "GSK3α/β knock-in mice showed increased stress-induced depression-like behaviors, while inhibiting the activity of GSK3β reduced depression symptoms." (PMID 36776771, 2022). "For instance, Baicalin exerts neuroprotective effects by inhibiting activation of the GSK3β/NF-κB/NLRP3 signaling pathway in a rat model of depression." (PMID 36452219, 2022). "GSK3β also plays a role in major depression; it is a target of mood stabilizers and antidepressants, and selective GSK3β inhibitors are shown to exert antidepressant action in rodents." (PMID 36776771, 2022). "Glycogen synthase kinase 3 beta has been shown to alter anxiety-, depression-, and addiction-related behaviors in rats, as well as neuronal activity in the shell of the nucleus accumbens." (PMID 35681342, 2022). "Downregulation of Ser9-phosphorylated GSK3β in the nucleus accumbens was observed in a mouse social defeat model of depression; meanwhile, increasing the expression of inactive GSK3β enhanced resilience to social defeat stress." (PMID 36776771, 2022). "Overall, these studies highlight the critical role of the GSK3β–Kv4.2 complex in the context of MSN maladaptive plasticity occurring in mouse models of depression." (PMID 35457230, 2022). "Consistent with previous studies, we found that Ser9 phosphorylation of GSK3β was reduced in the hippocampus of PPD mice, suggesting that the increased activity of GSK3β contributed to the anxiety and depression-like behaviors induced by gestational stress." (PMID 36776771, 2022).
depression (continued). "This indicated that the effect of IRN on improving CUMS-induced neuroinflammatory and depression-like behaviors was directly related to the regulation of the GSK-3β pathway." (PMID 35923544, 2022). "Increasing evidence suggests that GSK3β inhibitors are a potential therapeutic target for depression." (PMID 34051074, 2021). "Similarly, elevated GSK-3β mRNA levels were measured in the hippocampus of patients with major depression, and polymorphisms in the GSK-3β gene were reported in individuals with BD and major depression, and could be correlated with a therapeutic response to lithium." (PMID 35126052, 2021). "On the other hand, changes in expression and phosphorylation of GSK3β were reported in mouse models of stress-induced anxiety and depression." (PMID 34063830, 2021). "Activated GSK-3β has been reported in the brains of patients with depression, and GSK-3β inhibition is a therapeutic target for depression." (PMID 34381778, 2021). "GSK3β is suggested to be involved in the pathogenesis of depression, and is a target and/or modifier of antidepressant action." (PMID 34381778, 2021). "Data suggested that emodin inhibited hippocampal GSK3β activation during the development of depression." (PMID 34381778, 2021). "Further exploration of how 5-LO activates GSK3β is of great significance and is needed to understand the key role of inflammation in the occurrence of depression." (PMID 34381778, 2021). "GSK3β have been reported to be activated in the brains of mice exhibiting depression like behavior, as well as in the NAc of mice subjected to social defeat stress." (PMID 34121997, 2021). "Knocked down GSK3β expression with a novel adeno-associated viral vector (AAV2) and assessed changes in anxiety- and depression-like behavior and cocaine self-administration in GSK3β knockdown rats." (PMID 32694984, 2020). "Specific GSK3β inhibitors have anti-depressant effects and reduce depressive-like behavior in animal models of depression." (PMID 32188010, 2020). "Third, although sporadic clinical studies have measured changes in certain proteins like p11 and GSK3β in patients with depression or addiction, the results are similar to those in animal studies." (PMID 32694984, 2020). "GSK3B is decreased in expression in high memory states in our current work, and is mostly increased in expression in psychiatric disorders, including depression and stress related ones, suggesting an avenue to their impact on memory and on later life AD." (PMID 31792364, 2020). "The results suggest that the silencing of GSK3β in the NAc increases depression- and addiction-related behaviors, possibly by decreasing the intrinsic excitability of ChIs." (PMID 32694984, 2020). "In particular, the major components of the PI3K/Akt pathway, including GSK-3β and the mammalian target of rapamycin (mTOR), have been reported to act as depression and antidepressants." (PMID 32397675, 2020). "GSK-3β is involved in the process of neuroplasticity, contributes to the pathogenesis of depressive disorders, and plays a crucial role in the regulation of cellular homeostasis." (PMID 32992988, 2020). "Additional studies are required to establish the patterns and significance of interaction between Sigma1R, BDNF, and GSK-3β in the pathogenesis of depressive disorders." (PMID 32992988, 2020). "In depression, GSK3β abnormal activation suppresses BDNF expression, which regulates neural proliferation, neurogenesis, synaptic plasticity, and apoptosis." (PMID 30407505, 2019). "Chronic administration of corticosterone that models depression in mice impairs synaptic plasticity and upregulates GSK-3β activity—both of which are ameliorated by the administration of an antidepressant drug." (PMID 31191636, 2019). "Decreased activity of Akt and increased activity of GSK3β have been found in the prefrontal and occipital cortex of suicide victims with depressive disorder." (PMID 31275123, 2019).
depression (continued). "Activation of Akt leads to the phosphorylation of GSK3β, and the Akt/GSK3β pathways are important regulators of depression." (PMID 30622594, 2018). "PKC inhibition and acute stress increased P-S9 GSK3β levels, and this time promoted depression-like behaviors diminishing HINT1−/− mice’s swim activity." (PMID 28240305, 2017). "In an animal model for stress-induced depression, the induction of depression was found to be facilitated by activity of GSK3B and blocked by lithium." (PMID 29127487, 2017). "This provides compelling evidence that the PI3K/AKT/GSK-3β signaling pathway is an important contributor to depression." (PMID 28761074, 2017). "Here we demonstrated that the SCE treatment was able to activate PI3K/AKT/GSK-3β signaling pathway, as well to promote increased phosphorylated levels of related proteins, to improve the depressive syndromes in CUMS-induced mice." (PMID 28761074, 2017). "Mutant mice with a heterozygous GSK-3β deletion showed decreased evidence of depression in the FST, and infusion of L803-mts, a selective GSK-3 inhibitor, also decreased immobility in the same test." (PMID 27252679, 2016). "Although several animal studies on Alzheimer's disease have revealed that the ginsenoside Rb1 increases brain GSK-3β activity in vivo and in vitro, fewer reports have investigated such effects in depression model animals." (PMID 24523822, 2014). "GSK-3β is serine/threonine kinase, which has been acknowledged as a pivotal target for the treatment of depression and mania." (PMID 24396420, 2014). "Chronic citalopram treatment alleviated the depression-like behaviors and reversed the disruptions of the phosphorylated GSK3β in these animals." (PMID 24707399, 2014). "Inhibition of GSK3β with CT99021 relieves short-term synaptic depression, which is due to the contribution of GSK3β in activity dependent bulk endocytosis during neurotransmission." (PMID 23658842, 2013). "Lithium, an effective GSK3β inhibitor, has been used in treating depression and bipolar disorder for many years." (PMID 23626687, 2013). "Since we observed HA induced behavioral changes and Akt phosphorylation, our next step was to evaluate the Akt downstream target and depression mediator GSK3β using Western blot analysis." (PMID 24124534, 2013). "Taken together, these data support the possible existence of interactions between the GSK-3β/β-catenin pathway and other neurotransmitter systems involved in depression, including serotonin." (PMID 23862076, 2013). "Recent evidence suggested a role for GSK3β in regulating resilience in a social defeat model of depression." (PMID 22826345, 2012). "Consistent with a role for GSK3B in depression, fluoxetine increases phosphorylation of GSK3B at a specific N-terminal serine residue, thereby decreasing the kinase’s activity." (PMID 23075086, 2012). "Glycogen synthase kinase 3 beta (GSK3B) is an enzyme involved in energy metabolism and neuronal cell development, which are processes related to depression." (PMID 21494644, 2011). "This is consistent with data showing that inhibition of GSK3β is necessary to ketamine's rapid antidepressant action in a mouse model of depression (learned helplessness)." (PMID 21887357, 2011). "Depression of DNA-PKcs in HeLa cells leads to a decreased phosphorylation of Akt on Ser473 and its target GSK3β on Ser9, which, in other words, results in an increased activation of GSK3β." (PMID 20205745, 2010). "Therefore, improving Akt/GSK3β inhibitory control is an essential component of treatment for depressive disorders." (PMID 40431406, 2025). "Therefore, our results indicate that a reduction in DVL3 expression downregulates GSK3β, which prevents AD and depression in PS2 MT mice." (PMID 37501340, 2024). "Finally, the use of 666-15 suggested that miR-182-5p was involved in the regulation of depression via the Akt/GSK3β/CREB biosynthesis." (PMID 38038373, 2024).
depression (continued). "Some other DE mRNAs controlled by these pathways, such as glycogen synthase kinase-3 beta (Gsk3b) and the protein phosphatase 3 catalytic subunit alpha isoform (Ppp3ca), have also been suggested to be potential contributors to the development of depression." (PMID 37505566, 2023). "However, the relationship between the increase in phospho-GSK3β levels and improvement in the symptom severity of depression or mania was inconsistent." (PMID 36676744, 2023). "Glycogen synthase kinase 3 (GSK-3) is a serine/threonine kinase enzyme, which has two subunits, including GSK-3α and GSK-3β, the dysregulation of which could lead to mental disorders, including depression and cognitive impairment." (PMID 37881439, 2023). "Our results suggest that PBMC GSK3β could be a candidate biomarker for the differential diagnosis of bipolar disorder versus unipolar depression." (PMID 37807001, 2023). "Through additional protein-protein interactions that recalibrate protein phosphorylation, FKBP51 also impacts signaling of other depression-relevant pathways such as GSK3β, BDNF, and nuclear factor kappa B, linking it to inflammation and the immune system, as well as autophagy." (PMID 36203007, 2023). "An increase in the activity of GSK3β has been observed in the prefrontal cortex of patients and suicide victims with depression, as well as in the platelets of patients with depression." (PMID 36776771, 2022). "Moreover, many antidepressants can mediate depression-like behavior via activation of the AKT pathway, for example, by activating the AKT/ GSK3β /β-catenin signaling pathway in the hippocampus to attenuate alcohol-induced depression in mice." (PMID 35111368, 2022). "It has been proposed through animal models of depression that inhibition of GSK-3β may contribute to the antidepressant effect." (PMID 35923544, 2022). "Indeed GSK-3β-actuated molecular cascades have been reported to have modulatory influences on depression and anxiety disorders." (PMID 36055984, 2022). "Consistent with the involvement of the GSK3β/Kv4.2 axis in maladaptive plasticity in the CUMS model of depression-like behavior, the increased tLTP found in these mice has been associated with complementary modulation (decrease) in Kv4.2-mediated A-type K+ currents." (PMID 35457230, 2022). "As such, the GSK-3β signaling pathway may be an applicable therapeutic target and pathway for depression treatment." (PMID 35923544, 2022). "Findings indicating that it plays a crucial role hippocampal neuron development and survival suggest that regulation of GSK3β could be a clinical target for neuropsychiatric disorders, such as depression and anxiety disorders." (PMID 36055984, 2022). "Silencing of GSK-3β in NAc increases depression- and addiction-related behavior." (PMID 36172262, 2022). "Animal studies have also provided evidence for the involvement of GSK3β in depression." (PMID 36776771, 2022). "GSK-3β/β-catenin cascades have been reported that play a crucial role in the onset of depressive symptoms in animal models and thus have become a target of interest for depressive symptom alleviation and elucidation of the pathogenesis of depression." (PMID 36055984, 2022). "Moreover, GSK-3α and GSK-3β are activated in an environment of chronic oxidative stress, such as in BD, with greater activation in mania than in depression." (PMID 34295268, 2021). "Conversely, GSK3β overexpression in the nucleus accumbens induced a depression-like behaviors." (PMID 34051074, 2021). "In knockin mice in which one or the other isoform of GSK3 was mutated to a hyperactive form, those with hyperactive GSK3β (but not GSK3α) displayed heightened vulnerability to the learned helplessness model of depression-like behavior." (PMID 34063830, 2021). "GSK3B may be involved in the development of depression by inhibiting Erk-CREB-BDNF signaling, and PI3K/Akt/mTOR/GSK3B signaling may be the mechanism underlying the rapid antidepressant effects." (PMID 34976096, 2021).
depression (continued). "Therefore, GSK3β is suggested to be engaged in the pathogenesis of major depressive disorder, and to be a target and/or modifier of anti-depressants’ action." (PMID 32188010, 2020). "Additionally, a similar pro-depression-like effect can be induced by GSK3β overexpression in the nucleus accumbens, while the expression of inactive GSK3β mutant promotes resilience to social defeat stress." (PMID 32188010, 2020). "The aim of this study was to investigate the interaction between GSK-3β polymorphism (rs6438552, rs334558, and rs2199503) and negative life events in the pathogenesis of major depressive disorder (MDD)." (PMID 33658947, 2020). "However, it cannot be excluded that GSK3β-regulated inflammatory reaction within the peripheral immune system is the place of origin of the inflammation-induced depression." (PMID 32188010, 2020). "Although clinical studies are limited, we can presume that CHT, HCN2, GSK3β, and p11 may be important targets for the treatment of comorbid addiction and depression in the future owing to the findings from preclinical studies." (PMID 32694984, 2020). "Additionally, putative role(s) of GSK3β in the pathogenesis of depression and the influence of anti-depressants on GSK3β activity are discussed." (PMID 32188010, 2020). "The findings of another study also showed that resveratrol could ameliorate depression by activation of the Akt/GSK3β pathway and regulation of pro-inflammatory cytokines and apoptosis." (PMID 33292508, 2020). "Moreover, the PI3K-Akt/GSK3b pathway further regulates the induction and expression of inflammatory genes expression that contributes to the onset of depression." (PMID 32595452, 2020). "As people continue to explore the hypothesis related to depression, namely the hypothesis of mental illness and neuroplasticity, related research on glycogen synthase kinase (GSK-3β) (a key regulator of neuronal function) has increased." (PMID 33658947, 2020). "The increase on GSK3β activity has also been found in platelets of depressed patients, whereas the GSK3β gene expression was upregulated in such brain structures as the frontal cortex, raphe, and hippocampus in the rat model of depression." (PMID 32188010, 2020). "GSK3β in the NAc increases depression- and addiction-related behaviors." (PMID 32694984, 2020). "In this review, we highlight evidence collectively suggesting that inhibition of GSK3β acts as a multi-potent molecular mechanism that may mediate multi-potent effects of EPO on hippocampal volume changes in depression." (PMID 30310078, 2018). "A complex relationship between EPO, GSK3β, the hippocampus and depression may exist, in part, through nitric oxide (NO)-related pathways." (PMID 30310078, 2018). "Notably, in our experiments, the chronic lithium treatment known to amplified GSK3α phosphorylation at serine 21 and GSK3β at serine 9, is able to reverse the behavioral signs of anxiety and depression observed in Akt3 KO mice." (PMID 28442992, 2017). "Studies on human brains have evaluated the levels or activity of total GSK-3β protein in the prefrontal cortex in mood disorders, including depression, and increasing evidence suggests that inhibition of GSK-3β might contribute to antidepressant activity." (PMID 27252679, 2016). "Unexpectedly, floating behaviour and brain glycogen synthase kinase-3 beta (GSK-3beta) mRNA levels, a factor of synaptic plasticity as well as a marker of distress and depression, were increased during the additional swimming session that was prevented by imipramine." (PMID 27478647, 2016). "Moreover, the MS-induced activity of the GSK-3β-CREB signaling pathway is a possible mechanism of depression." (PMID 26798520, 2015). "Results implied that MS induces depression-like behavior and the effects may be mediated partly by interfering with the hippocampal GSK-3β-CREB signaling pathway and by reducing the levels of some plasticity-related proteins." (PMID 26798520, 2015).